MMP13 (matrix metallopeptidase 13)
Diseases named in the same sentence as MMP13 in open-access papers (continued):
Sharing a sentence is not in itself a finding about the gene and the disease.
Arthritis (continued). "In a mouse arthritis model, FSTL-1 significantly reduced the expression of IL-6 and MMP-13, thereby reducing joint destruction and synovial inflammation." (PMID 33936382, 2021). "Oral intake of a mixture of Acacia catechu water extract and Morus alba root bark ethanol extract (50 mg/kg BW) has anti-inflammatory (TNF-α and IL-1β), collagenase (MMP-13) inhibitory, and articular cartilage protective activities in MIA-induced arthritis." (PMID 33371279, 2020). "In murine models, F2r-/- mice that lack PAR1 have reduced degradation of cartilage and expression of cytokines and MMP13 in SF, while swelling was reduced after PAR2 blockade in a model of joint inflammation." (PMID 33763056, 2020). "Rats treated with UP1306 showed statistically significant improvements in arthritis severity markers, including uCTX-II (91.4% vs. collagen-induced arthritis (CIA)), serum IL-1β, TNF-α, and IL-6 levels as well as synovial MMP-13." (PMID 30691120, 2019). "Overall, it can be concluded that the silencing of miR‐10a‐5p plays a paramount role in arthritis by regulating and promoting proinflammatory cytokines, TLR3 and MMP13 as well." (PMID 28782180, 2018). "It has been previously shown that MMP-13 is overexpressed in OA and RA and recent reports provide evidence that anti-MMP-13 therapy is a promising new strategy for treatment of arthritis." (PMID 24385683, 2013). "Therefore, MMP-13 may be a novel target for developing new strategies for treatment of arthritis." (PMID 24385683, 2013). "However, the mild pannus formation and cartilage destruction observed in the MMP-13–/– mice might be due to compensation by other proteases such as cathepsin K, which have been shown to be involved in joint destruction in the collagen-induced arthritis model." (PMID 24369907, 2013). "In murine AIA, significant and temporal changes in cytokines (IL-1β, TNFα, IFN-γ, IL-6) and factors that govern extracellular matrix turnover (MMP-3, MMP-13, TIMP-1) occur during the acute phase, Days 1 to 3 after arthritis induction." (PMID 20307272, 2010). "IFN-γ-stimulated arthritis induced a marked increase in MMP-3, MMP-12 and MMP-13 mRNA levels in the cartilage layers of both WT controls and p47phox-/- mice, in comparison with the cartilage of naive knee joints (Δ Ct ranging from 3 to 9)." (PMID 15987491, 2005). "MMP3 and MMP13 are arthritis-related genes, while Cdkn genes that negatively regulate cell proliferation and are often considered to be related to cell senescence." (PMID 39220112, 2024). "MMP9, which inhibits both angiogenesis in the pannus and the activation of pro-MMP13 in SF, may play a pivotal role in the development of a MMP inhibitor and therapeutic drug for arthritis." (PMID 35329213, 2022). "In conclusion, TAP2 could effectively attenuate MIA-induced arthritis in rats by blocking TLR4 and its successive inflammatory cytokines and MMP13." (PMID 33060735, 2020). "Furthermore, a function study reported that the S100A8 stimulation in chondrocytes induces upregulation of mRNA levels of MMP-2, MMP-3, MMP-9, and MMP-13 and ADAMTS-4 and ADAMTS-5 in experimental murine arthritis, which is similar to our findings." (PMID 31815654, 2019). "In addition, several transcripts with known roles in arthritis were positionally enriched in specific joint locations including MMP1, MMP13, interleukin (IL) 1R, IL34 and CXCL12 (refs 17, 18, 19, 20)." (PMID 28332497, 2017). "Clinical severity of arthritis was higher in WT mice compared with MMP-13–/– mice (day 8 (mean ± standard deviation): inflammation score, 6 ± 0.5 in WT mice and 1.8 ± 0.5 in MMP-13–/– mice, P <0.05; destruction score, 1.5 ± 0.5 in WT mice and 0.6 ± 0.5 in MMP-13–/– mice, P <0.0043)." (PMID 24369907, 2013). "In addition, a recent study indicated that blocking TLR4 could effectively attenuate monoiodoacetate-induced arthritis in rats by relieving joint pain and reducing the expression of TNF-α, IL-1β, and matrix metallopeptidase-13 (MMP13)." (PMID 36785752, 2023).
Arthritis (continued). "Moreover, the cartilage in NC group showed almost negative Mmp13 immunoreactivity, whereas that in the arthritis model expressed stronger Mmp13 immunoreactivity with larger positive area (P<0.01 versus NC)." (PMID 31089001, 2019). "Indeed, treatment of RA mice with selective inhibitors of MMP-13 reduced the mean arthritic score in comparison to control mice, and MMP-13 knockout mice were protected from collagen antibody-induced arthritis, suggesting that MMP-13 inhibition could have a therapeutic value." (PMID 38543230, 2024). "Although this was demonstrated in an arthritis model, it is possible that this mechanism is used in different disease states including BC such that fibronectin fragments generated by PIP activity may also upregulate the expression of MMP3 and MMP13 in the 4T1-PIP tumors." (PMID 33777801, 2021).
liver fibrosis (64 papers, 2009 to 2025). "Over expression of TIMP-1 is associated whit liver fibrosis, while MMP-13 cleaves and inactivates CCL2, CCL7 and CXCL12 leading to reduction in chemotaxis, as well as to a decrease in the fibrosis process." (PMID 29040281, 2017). "As described by others, MMP13 is critical for resolution of liver fibrosis in mice and is associated with a resolution-associated macrophage population called scar-associated macrophages (SAMs)." (PMID 27042213, 2016). "Furthermore MMP-13 expression is restricted to regions of liver fibrosis rich in scar-associated macrophages." (PMID 23259590, 2012). "However, some authors suggest strong profibrotic role of macrophage derived MMP13, as they observed that liver fibrosis was suppressed, along with fibrotic markers and inflammatory mediator expression, in MMP13-deficient mice during cholestasis-induced liver fibrosis." (PMID 26568664, 2015). "During the regression phase of liver fibrosis, MoMφs can participate in ECM degradation by secreting MMPs such as MMP9, MMP12, and MMP13, which facilitates the regression of liver fibrosis." (PMID 39635524, 2024). "On the one hand, a protective role was shown demonstrating decreased accumulation of ECM and a lower number of αSMA+ cells upon overexpression of MMP13 in the chronic CCL4-induced model of liver fibrosis." (PMID 37207229, 2023). "Matrix Metallopeptidase 13 (MMP13) is involved in the degradation of newly formed matrix during the recovery of liver fibrosis in rats." (PMID 34122138, 2021). "Mmp13 is involved in the degradation of hepatic ECM in the initial phase of hepatic fibrosis and pave the way for the proliferation of activated HSC that transforms into myofibroblasts." (PMID 33269546, 2021). "We believe that these results will provide important theoretical and experimental bases needed to control interstitial MMPs (MMP-1 in humans and MMP-13 in rats) and lead to the resolution of liver fibrosis." (PMID 27412967, 2016). "Because we did not detect alterations in scar formation in the macrophage MMP-14 mouse mutants, it is conceivable that collagenolytic activity in scar derives from another enzyme, possibly MMP-13, that is pivotal in this process in liver fibrosis." (PMID 27066886, 2016). "In one study, treatment with curcumin also increased serum MMP-13 and glutathione levels, thus reversing fibrosis in CCl4-induced liver fibrosis in rats." (PMID 25897319, 2015). "Respectively, production of MMP13 by Kuppfer cells was shown to be sufficient in preventing pig serum-induced rat liver fibrosis." (PMID 26568664, 2015). "In a mouse model of liver fibrosis, the BM-derived cells express matrix metalloproteinase (MMP)-13 and MMP-9 and contribute to the regression of liver fibrosis." (PMID 25551560, 2014). "For instance, as a potential antifibrotic target, studies suggest enhanced expression of MMP13 attenuates liver fibrosis with reduced collagen levels." (PMID 24971829, 2014). "Whereas MMP-13 was recently shown to play a role in the pathogenesis of liver fibrosis, the role of MMP-13 in lung fibrosis remains to be established." (PMID 24023851, 2013). "Scar-associated macrophages have been shown to be the principal source of MMP-13 in a rodent model of liver fibrosis." (PMID 23259590, 2012). "Mmp13 has been shown to be expressed by macrophages in murine livers where it is involved in mediating the regression of hepatic fibrosis and MMP-13 activity against fibrinogen has been shown in vitro." (PMID 21326869, 2011). "Notably, MMP13, another key enzyme involved in matrix remodeling during the regression phase of liver fibrosis, was also analyzed in our study." (PMID 40873954, 2025). "Interestingly, divergent functions were reported for MMP13 in experimental models of liver fibrosis." (PMID 37207229, 2023).
liver fibrosis (continued). "Furthermore, hepatic mRNA levels of fibrogenic genes (Acta2, Col1a1, Col3a1, Col4a1, Tgfb1, Mmp13 and Vim) were significantly upregulated in miR-223KO mice compared with WT mice, suggesting that miR-223 deletion accelerated liver fibrosis." (PMID 33867837, 2021). "Hepatic protein levels of TGF-β1, known for pro-fibrogenic cytokine to promote HSCs activation or proliferation were drastically normalized by GF and other proteins such as TIMP-1, MMP-1, and MMP-13 which are known as ECMs promoters or degradations as responses of liver fibrosis." (PMID 34829709, 2021). "Atractylodes macrocephaia was found: to recover the elevated levels of hyaluronic acid, laminin, type IV collagen, type III procollagen, and TGF‐β1; to suppress procollagen I, collagen III, and TIMP‐1 expression; and to improve the TIMP‐1/MMP‐13 ratio in rat liver fibrosis." (PMID 32705795, 2020). "Taken together, we have provided the first demonstration that BM-MSC transplantation can promote the activation of M2 macrophages expressing MMP13 and inhibition of M1 macrophages to further inhibit hepatic stellate cells (HSCs), which play synergistic roles in attenuating liver fibrosis." (PMID 30635047, 2019). "However, transplantation of BM-MSCs effectively promoted the proliferation and activation of M2 macrophages expressing MMP13 and inhibited M1 macrophages to suppress the activation of HSCs, which together played synergistic roles in degrading liver fibrosis." (PMID 30635047, 2019). "Hence, we concluded that transplantation of BM-MSCs attenuated liver fibrosis by activating M2 macrophages, which were able to express MMP13." (PMID 30635047, 2019). "Indeed, in the context of liver fibrosis, myeloid cells, including macrophages, neutrophils and dendritic cells are important sources of MMP-13 and MMP-9, respectively." (PMID 28118605, 2017). "Progression of liver fibrosis is associated with decreased matrix degradation due to inhibition of matrix metalloproteases (mostly MMP-8 and MMP-13), which is the result of increased expression of their natural inhibitor TIMP-1, something observed in treated LX2 cells." (PMID 24637780, 2014). "This notion is also supported by a recent report showing that MMP-13 during the initial phase of fibrogenesis, could be important for the cleavage of newly formed matrix in an experimental model of hepatic fibrosis." (PMID 22911824, 2012). "Besides this, MMP13 has been shown to play a less straightforward role in liver fibrosis." (PMID 40261813, 2025). "Importantly, MMP13 was expressed by activated M2 macrophages in our present study, which accounted for the positive connection between the activation of M2 macrophages and attenuation of liver fibrosis." (PMID 30635047, 2019). "We also noted that pathological process of liver fibrosis of the animals was significantly ameliorated due to re-construction of M1 macrophage-dominant immune environment by increasing matrix metalloproteinase 13 (MMP13) secretions and facilitating HSC apoptosis in vivo." (PMID 30034399, 2018). "Interestingly, with development of bridging fibrosis at week 52, changes in pathways related to hepatic fibrosis/hepatic stellate cells activation decreased as compared to 24 weeks and were mainly limited to increase in genes for Col4a1, Mmp12, Mmp13 and Vcam1." (PMID 29222421, 2017). "However, we have previously reported that stem cells derived from bone marrow changed their phenotypes of MMP-13 (a major interstitial collagenase in rodents with homology to human MMP-1) to MMP-9 expression in the recovery phase from experimental liver fibrosis and cirrhosis." (PMID 24978432, 2014). "Instead, they demonstrated an increase in TIMPs mRNA transcripts and postulated that the balance between the down-regulation of MMP-13 expression and the up-regulation of the expression of TIMPs may result in the deposition of type I collagen in experimental hepatic fibrosis." (PMID 24978432, 2014).
liver fibrosis (continued). "Ly-6Clo subgroup macrophages primarily repair liver fibrosis by upregulating MMPs (MMP9, MMP12, and MMP13), which facilitates the degradation of ECM." (PMID 39635524, 2024). "Diverse MMPs can degrade fibrillar-type collagen, as in liver fibrosis, but MMP-8, MMP-1, and MMP-13 have proven to display the main activity." (PMID 37681859, 2023). "Lumican‐null mice have a significantly less severe extent of hepatic fibrosis and significantly higher protein level of α‐SMA and MMP‐13." (PMID 32910552, 2020). "Over expression of MMP-1, MMP-8 and MMP-13 was shown to reduce the number of activated HSC and attenuate the hepatic fibrosis when transiently over expressed in the liver." (PMID 30679661, 2019). "We further analyzed MMP-2, MMP-9, MMP-13 and tissue inhibitor of matrix metalloproteinases 1 (TIMP-1) hepatic gene expressions after BDL- and CCl-4-induced liver fibrosis using RT-PCR." (PMID 30875826, 2019). "Meanwhile, the mRNA expression levels of Acta2, MMP13, Coll1a1, and TIMP1 were examined, which are all classical profibrogenic markers during liver fibrosis process." (PMID 29464186, 2017). "In a Schistosoma mansoni model of pulmonary fibrosis, Madala and colleagues demonstrate the intricate balance between MMP12 and MMP13 in modulating TH2-dependent lung and liver fibrosis." (PMID 27689529, 2016). "Macrophages contribute to ECM remodeling during both the injury and recovery phase of CCl4-induced liver fibrosis and are an abundant source of MMP-9 and MMP-13." (PMID 27672655, 2016). "Consistent with a previous study in mice fed the MCD diet, expression levels of MMP-2, MMP-13, TIMP-1, and TIMP-2 were increased in mice with MCD diet-induced hepatic fibrosis in this study." (PMID 24066058, 2013). "In addition, MSCs upregulate MMPs (e.g., MMP9 and MMP13) and inhibit the expression of TIMPs (e.g., TIMP-1), which directly degrade ECM to alleviate liver fibrosis." (PMID 38360740, 2024). "MMP-13 and TIMP-1 play a crucial role in modulation of liver fibrosis in rodents." (PMID 31118972, 2019). "Macrophages located almost exclusively in areas of liver tissue scarring are a major source of MMP13 and can resolve liver fibrosis both directly by production of MMP13 and indirectly by secretion of cytokines, such as TNF-α and IL-1, which regulate MMP13 production by other cells." (PMID 30034399, 2018). "In vitro studies using isolated hepatic stellate cells from rat liver proved that MMP‐13 is involved in the cleavage of both CTGF and TGF‐β1, thus play a significant role in the pathogenesis of hepatic fibrosis through modulation of the processing of profibrogenic molecules." (PMID 28782260, 2017). "Furthermore, the study suggests that blocking of MMP‐13 and CTGF has potential therapeutic implications to arrest liver fibrosis." (PMID 28782260, 2017). "Hepatic fibrosis was induced using intraperitoneal injections of N‐nitrosodimethylamine (NDMA) in doses of 10 μg/g body weight on three consecutive days of each week over a period of 4 weeks in both wild‐type (WT) and MMP‐13 knockout mice." (PMID 28782260, 2017). "Stimulation of liver fibrosis in AnxA1-KO animals was unrelated to regulation of hepatic TGF-β1 or of MMP-9 and MMP-13, suggesting that additional factors may contribute to the profibrogenic evolution of NASH." (PMID 24668763, 2014). "In addition, scar resolving properties were recently ascribed to MΦ in the resolution of a different kind of collagen-based scar, during hepatic fibrosis, in which the same MMP described here, MMP-13, plays a fundamental role, as well." (PMID 22205935, 2011). "The ratio of MMP9/TIMP1 and MMP13/TIMP1 showed increments in the liver after chlorophyllin treatment, indicating that administration of chlorophyllin may promote the fibrolysis and resolving liver fibrosis." (PMID 30564133, 2018).
liver fibrosis (continued). "Moreover, the increasing expression of relative genes with liver fibrosis (TGF-β, α-SMA, MMP-13) also demonstrated hepatic fibrosis initiation on the 30th day of excessive nutrition intake and gradually aggravated the severity of liver fibrosis from the 30th to 50th day." (PMID 28820447, 2017). "Alternatively, elevation of these mRNA might be accompanied with acute liver injury because MMP-13 was reported to express in CCl4-induced acute liver injury, and because expression of MMP-2 was reported to increase in the aggressive phase of liver fibrosis but decrease in the repair stage." (PMID 27547834, 2016). "With the improvement in liver fibrosis, the mRNA levels of tissue inhibitor of metalloproteinase-1 (TIMP-1) and matrix metalloproteinase-2 (MMP-2), two genes involved in hepatic fibrogenesis, were found to be significantly suppressed, while TIMP-2 and MMP-13 were unaffected." (PMID 24066058, 2013). "However, these subtle increases in MMP-2 and MMP-13 expression after reconstitution with VHLfl/fl/VEGFfl/fl-LysMCre+ BM, although statistically significant, are obviously not sufficient to accelerate the resolution of liver fibrosis." (PMID 28118605, 2017). "Furthermore, LV-gra15II-M greatly reduced the secretion of TGF-β1, increased the expression of MMP13, and promoted the apoptosis of HSC without prominent injury of hepatocytes in experimental mouse liver fibrosis." (PMID 30034399, 2018).